WNT1 (Wnt family member 1)
Diseases named in the same sentence as WNT1 in open-access papers (continued):
Sharing a sentence is not in itself a finding about the gene and the disease.
breast cancer (continued). "WNT family member 1 (WNT1) has been identified as a target of miRNA-34a (miR-34a), and it has been found that miR-34a can affect colon cancer progression and inhibit breast cancer proliferation via inactivation of the WNT/β-catenin pathway." (PMID 32301035, 2020). "FAK deletion in Wnt1-driven mammary tumor did not change tumor cell proliferation but increased apoptosis which likely also contributes to the reduced tumor growth and metastasis in this model." (PMID 32493400, 2020). "Although this association is not well studied, in an experiment that was performed using an animal model of HER-2-positive breast cancer, CCL2, which is produced by cancer and myeloid cells, attracted macrophages to upregulate Wnt-1 and downregulate E-cadherin, resulting in cancer dissemination." (PMID 32580398, 2020). "We found that FAK deletion did not change survival of Wnt1-driven mammary tumor cells under stress conditions including serum or amino-acid starvation." (PMID 32493400, 2020). "HNK inhibits leptin-induced Wnt1, MTA1 and β-catenin expression in breast cancer cells." (PMID 26036628, 2015). "Thus, in order to create a humanized model of MMTV signaling, we recombinantly over-expressed WNT1 and FGF3 in MCF7 cells, an ER(+) human breast cancer cell line." (PMID 26421711, 2015). "Thus, to develop a humanized model of MMTV signaling, we over-expressed WNT1 and FGF3 in MCF7 cells, an ER(+) human breast cancer cell line." (PMID 26421711, 2015). "In addition, Pygo2 can facilitates histone methyltransferase (HMT) and histone acetyltransferase (HAT) interaction with β-catenin and further augment Wnt1-induced, TCF/LEF-dependent transcriptional activation in breast cancer cells." (PMID 25871475, 2015). "For example, E2 administration to ERα knockout mice bearing the Wnt-1 oncogene significantly increases mammary tumor incidence, and even in the absence of ERα, aromatase inhibitors decreased tumor formation induced by Wnt-1." (PMID 25569080, 2015). "Downregulation of FGFR1 signaling in the established Wnt1/iR1 mammary tumors resulted in rapid regression to a nonpalpable state." (PMID 26581390, 2015). "Our finding that HNK modulates Akt, GSK3β, and β-catenin, key components of leptin-signaling network in breast cancer cells, prompted us to further explore whether HNK treatment can also inhibit MTA1, Wnt1, β-catenin and cyclin D1 in the presence of leptin." (PMID 26036628, 2015). "For instance, mice lacking the Wip1 phosphatase (also known as PPM1D; protein phosphatase magnesium-dependent 1D) have a delay in HER2/neu (human epidermal growth factor 2), but not Wnt1-induced mammary tumor formation." (PMID 23369183, 2013). "Two genes, Wnt1 and Wnt 5b, were significantly down-regulated in ATF3-induced mammary tumors." (PMID 21304988, 2011). "About half of the bi-transgenic mice examined (n = 23) developed palpable mammary tumors by the age of 19 weeks (T1/2 = 19), whereas fewer than 30% of the Wnt1 transgenic and none of the ILK or FVB control mice had tumors." (PMID 20565980, 2010).
breast cancer (continued). "Strikingly, the ΔNPEA3En:Wnt1 expression ratio was substantially reduced in mammary tumors relative to non-tumorous mammary glands from bigenic MMTV/Wnt1, MMTV/ΔNPEA3En mice (P = 0.01)." (PMID 20107508, 2010). "Wnt1 was the first identified oncogene activated by mouse mammary tumor virus insertional mutagenesis, establishing the potential of aberrant WNT expression to promote mammary cancer." (PMID 19473496, 2009). "Our results, showing that Wnt1 transactivates EGFR in tumor cell lines, imply that, in breast cancer, constitutive WNT signaling might impact not only on the canonical pathway, but also on EGFR activity by stimulating ligand availability." (PMID 17897439, 2007). "We conclude that functional Id2 expression is not required for Wnt1 to induce mammary hyperplasia and mammary tumors." (PMID 15601467, 2004). "Experiments on transgenic mice showed that overexpression of Wnt-1 or its downstream effectors β-catenin or c-Myc under the control of the MMTV promoter resulted in development of hyperplastic mammary glands that mainly comprised progenitor cells and mammary tumors derived from these cells." (PMID 41303422, 2025). "In contrast, no lung metastases were found in mice with WNT1‐driven mammary tumors." (PMID 36106661, 2022). "Wnt1 signaling, including both canonical and non-canonical, plays a key role not only in embryogenesis but also in the development of several cancers, such as breast cancer." (PMID 35756611, 2022). "Likewise, through WNT-1 inhibition, the miR-148a overexpression decreased the metastatic potential and lung colonization of murine 4T1 and human MDA-MB-231 cells in vivo, supporting the role of miR-148a as a breast cancer metastasis biomarker for the clinic." (PMID 36012638, 2022). "Interestingly, the overexpression of both Prune-1 and Wnt1 in the mammary glands did not alter mammary tumor onset, compared with the MMTV–Wnt1 mice." (PMID 33426510, 2021). "Moreover, it is interesting to note that there is a difference between vasculature of breast cancer induced by either Her2+ where anti CXCL12 agents are not effective in contrast to Wnt1 derived tumors." (PMID 34445691, 2021). "In contrast to the role in ER− breast cancer (basal-like and ErbB2+) summarized above, CD151 appears to be tumor suppressive in some cases, for example, during the development and growth of ER+ mammary tumors in the mouse mammary tumor virus (MMTV) promoter-driven Wnt1 oncogene model." (PMID 33919420, 2021). "However, Wnt1 is not expressed in the normal mammary gland and is not overexpressed in human breast cancer." (PMID 25149534, 2014). "It is thought that the ability of cyclin D1 to activate CDK4 is critical for driving tumorigenesis, and that CDK4-associated kinase activity is required to maintain this tumorigenesis, as shown in mice with Her2-induced, but not Wnt-1-induced and Ras-induced breast cancer." (PMID 23336272, 2013). "Thus, partial SAFB1 loss does not accelerate the formation, or alter the incidence of Wnt-1 induced mammary tumors." (PMID 19267898, 2009). "Mice expressing Wnt-1 under the control of the enhancer elements in the MMTV long terminal repeat develop extensive hyperplasias of the mammary glands at prepubertal ages, mammary tumors at a median age of 6 months, and sometimes pulmonary metastases (; Podsypanina K, unpublished observations)." (PMID 16207355, 2005). "By showing that forced expression of Wnt1 in the mammary gland is capable of overcoming the block to proliferation caused by the absence of Id2, we conclude that functional Id2 expression is not required for Wnt1 to induce mammary hyperplasia and mammary tumors." (PMID 15601467, 2004).
breast cancer (continued). "Indeed, mice lacking LRP5 form Wnt1-induced mammary tumors much later than wild-type mice." (PMID 29854300, 2018). "In addition, we provide unanticipated, novel evidence suggesting cooperation between the Wnt1 and ILK pathways, resulting in upregulation of FOXA1/ER-α transcriptional network and the expansion of the luminal progenitor cells, leading to accelerated breast cancer development." (PMID 20565980, 2010). "To put this poorly differentiated RSPO3 tumor phenotype into further perspective, we comparatively analyzed WNT1‐driven mammary tumors that developed in the co‐bred MMTV‐Wnt1;Rspo3inv cohort (only Wnt1 transgene expression, given the lack of Cre)." (PMID 36106661, 2022). "cKD-Wnt1 mice developed tumors with a slightly increased median latency at 172 days and an overall very similar time course as Ctrl-Wnt1 mice, suggesting that FAK kinase activity was not required for mammary tumor development in this mouse model." (PMID 32493400, 2020). "We demonstrated that SDF1 is important for Wnt1, but not for HER2, in inducing murine mammary tumor and the role of SDF1 in tumorigenesis involves Gr1+ myeloid cells to facilitate growth and/or angiogenesis." (PMID 20087418, 2010). "To address Wnt-driven triple-negative breast cancer specifically, we focused on the Wnt1 and EGF receptor pathways, since these are 2 predominant drivers of oncogenic signaling in ER- and HER2-negative breast cancers that converge downstream on Myc and Ras effector pathways." (PMID 31611367, 2019).
osteoporosis (62 papers, 2013 to 2025). A condition of reduced bone mass, with decreased cortical thickness and a decrease in the number and size of the trabeculae of cancellous bone (but normal chemical composition), resulting in increased fracture incidence. "Some mutations in genes that participate in WNT1 signaling, like WNT1, can lead to early-onset osteoporosis and osteogenesis imperfecta." (PMID 40496246, 2025). "In 2013, WNT1 was identified as the causative gene of the early-onset osteoporosis (EOOP) and osteogenesis imperfect (OI) in humans." (PMID 39283365, 2025). "Case 15 involved late-onset diseases without current clinical manifestations; there is an increased likelihood of osteoporosis due to multiple WNT1 gene variants, which necessitates regular follow-up." (PMID 40832109, 2025). "Biallelic pathogenic WNT1 (wingless-type mmtv integration site family, member 1) variants are associated with Osteogenesis Imperfecta, and monoallelic pathogenic variants cause an autosomal dominant form of early-onset osteoporosis." (PMID 40362441, 2025). "Monogenic forms, often syndromic, were linked to mutations in genes such as COL1A1, COL1A2, and WNT1, whereas multifactorial osteoporosis, particularly postmenopausal, was associated with variants in LRP5, SOST, VDR, and other GWAS-identified loci." (PMID 40772209, 2025). "Given that WNT1 heterozygous variants caused dominantly inherited early onset osteoporosis, it is worthy to explore the impact of WNT1 variants in the osteoporotic population of Chinese ethnic." (PMID 39126373, 2024). "Children with biallelic WNT1 variants present with severe skeletal fragility mimicking OI type III, while heterozygous WNT1 variants lead to an osteoporosis phenotype that manifests often only later in childhood or in adulthood." (PMID 37668887, 2024). "WNT1 is a known gene for monogenic osteoporosis, with 35 reported loss-of-function variants affecting osteoblast differentiation and function." (PMID 39273077, 2024). "This study focuses primarily on pathogenic or rare suspicious variants in low-density lipoprotein receptor-related protein 5 (LRP5), plastin 3 (PLS3), or proto-oncogene Wnt-1 (WNT1) as monogenic causes of osteoporosis." (PMID 37277619, 2023). "Pathogenic variants in the LRP5, PLS3, or WNT1 genes can significantly affect bone mineral density, causing monogenic osteoporosis." (PMID 37277619, 2023). "Subsequent genome-wide association studies have demonstrated that Wnt has a direct effect on BMD, and it was recently shown that mutations in Wnt1 are involved in osteoporosis and hyperostosis." (PMID 37108563, 2023). "Among the 19 human WNT ligands, WNT16 affects cortical bone properties and homeostasis, and patients with early-onset osteoporosis have been observed to have a high frequency of heterozygous mutations in the WNT1 gene." (PMID 37958752, 2023). "In conclusion, the results of our study suggest a potential role of heterozygous WNT1 variants in the pathogenesis of early-onset osteoporosis." (PMID 36004351, 2022). "While traditional biomarkers for bone turnover tend to be normal in WNT1 mutation-positive subjects with osteoporosis, the patients have a unique miRNA profile in serum." (PMID 34236445, 2022). "While the autosomal dominant WNT1 osteoporosis affects both sexes similarly, the X-linked PLS3 presents predominantly in males while females portray a variable phenotype from normal BMD to skeletal fragility with fractures." (PMID 36157448, 2022). "The pathogenic mechanisms of early-onset osteoporosis caused by WNT1 and PLS3 mutations are incompletely understood and diagnostic biomarkers of these disorders are limited." (PMID 36157448, 2022). "WNT1 has been linked to bone physiology in humans, as LoF mutations can cause early-onset osteoporosis or osteogenesis imperfecta (OI)." (PMID 35052478, 2022).
osteoporosis (continued). "As a matter of fact, literature data confirm that individuals harboring heterozygous WNT1 missense variants have a different clinical phenotype, ranging from normal or slightly reduced bone mass to early onset osteoporosis." (PMID 36004351, 2022). "In contrast, WNT1-associated autosomal dominant early-onset osteoporosis, caused by heterozygous variants, has been reported less frequently." (PMID 34236445, 2022). "Another study reported myelofibrosis in one young adult with WNT1 osteoporosis and increased bone marrow fibrosis in other individuals with the same heterozygous WNT1 variant." (PMID 34236445, 2022). "Co-occurrence of COL1A1 and WNT1 mutations was found in a patient with a mild OI phenotype but severe osteoporosis." (PMID 34394176, 2021). "In OI, studies have shown that biallelic mutations in WNT1 result in recessive OI, whereas heterozygous mutations in WNT1 are associated with early-onset osteoporosis in dominant hereditary families." (PMID 34078411, 2021). "Mutations in WNT1 are associated withosteogenesis imperfecta and with early onset osteoporosis, which isphenocopied in mice carrying the human WNT1 mutation orwith a cell-specific deletion of Wnt1 in the osteoblastlineage." (PMID 34009051, 2021). "Mutations in the WNT1 gene are found in families with osteogenesis imperfecta (OI) type XV and early-onset osteoporosis." (PMID 32328030, 2020). "miR-31-5p was found to be downregulated in patients with WNT1 osteoporosis, a primary osteoporosis due to heterozygous p.C218G WNT1 mutation." (PMID 32664424, 2020). "Mutations in Wnt1 have been shown to be responsible for osteoporosis and osteogenesis imperfecta, and transgenic overexpression of Wnt1 has been shown to markedly increase bone mass in mice." (PMID 33085187, 2020). "The sclerostin antibody has been suggested to be an effective treatment option for WNT1 mutation-related osteoporosis." (PMID 32733380, 2020). "Deletion of Wnt1 in osteocytes results in low bone mass and increased fracture risk, similar as WNT1 mutation-related osteoporosis." (PMID 32733380, 2020). "Assessing treatment response according to the genetic aetiology has been investigated in patients with early‐onset low‐turnover osteoporosis due to WNT1 or PLS3 mutations who were shown to respond to teriparatide therapy." (PMID 30357886, 2019). "So far, studies have shown involvement of the WNT pathway in osteoarthritis and osteoporosis, while more recent studies uncovered that mutations in WNT1 cause osteogenesis imperfecta and early-onset osteoporosis." (PMID 31382613, 2019). "In human, monoallelic mutation at WNT1 would lead to inherited early onset of osteoporosis, whereas biallelic mutations would lead to osteogenesis imperfecta." (PMID 30680358, 2019). "Mutations in WNT1have been associated with extreme phenotypes of osteoporosis, such as prenatally-onset severe OI, idiopathic juvenile osteoporosis and pregnancy-associated osteoporosis, confirming WNT1’s central role in regulation of bone strength." (PMID 30447692, 2018). "More recently, the study of subjects with extreme phenotypes of osteoporosis, such as idiopathic juvenile osteoporosis and pregnancy-associated osteoporosis has yielded WNT1 and PLS3 as novel regulators of bone strength." (PMID 27533615, 2016). "Wnt1 mutations result early-onset osteoporosis and osteogenesis imperfecta in humans and reduce mineralization of MC3T3 cells." (PMID 26030407, 2015). "Interestingly, heterozygous dominant mutations in WNT1 cause early-onset osteoporosis; likewise, mutations in LRP5 result in both dominant and recessive forms of osteoporosis." (PMID 41410595, 2025). "Among monogenic causes, WNT1-related osteoporosis has been described in children and adults." (PMID 41128774, 2025). "A heterozygous Wnt1 mutation (p.R235W) has been identified in early-onset osteoporosis patients." (PMID 39283365, 2025).